ZUP1 (zinc finger containing ubiquitin peptidase 1)
Description:
Deubiquitinase with endodeubiquitinase activity that specifically interacts with and cleaves 'Lys-63'-linked long polyubiquitin chains. Shows only weak activity against 'Lys-11' and 'Lys-48'-linked chains. Plays an important role in genome stability pathways, functioning to prevent spontaneous DNA damage and also promote cellular survival in response to exogenous DNA damage. Modulates the ubiquitination status of replication protein A (RPA) complex proteins in response to replication stress.
Synonyms: DUB; C6orf113; ZUFSP; dJ412I7.3
Tractability: Small molecule: a structure with a bound ligand is known. PROTAC: ubiquitination databases record sites on it.
Gene: Protein-coding gene on chromosome 6 (116,635,616 to 116,668,812, reverse strand). Ensembl gene ENSG00000153975.
Subcellular location: Cytoplasm; Nucleus
Subcellular location (Human Protein Atlas): Nucleoplasm; Cytosol
Gene Ontology:
Molecular function: cysteine-type deubiquitinase activity; protein binding; DNA-binding transcription factor activity; transcription cis-regulatory region binding
Biological process: regulation of DNA-templated transcription
Cellular component: cytoplasm; cytosol; nucleoplasm; nucleus
Genetic constraint (gnomAD): Loss-of-function variants: 42 observed, 48.56 expected, observed/expected ratio (o/e) 0.86, 90% interval 0.68 to 1.12. The upper end of that interval is the gene's LOEUF score, 1.12, which puts it in group 4 of 6, group 1 being the genes least tolerant of losing a copy. Missense variants: 571 observed, 583.67 expected, observed/expected ratio (o/e) 0.98, 90% interval 0.91 to 1.05. Synonymous variants: 186 observed, 194.85 expected, observed/expected ratio (o/e) 0.95, 90% interval 0.85 to 1.08.
Homologues: Orthologues: chimpanzee ZUP1 (99% identical), macaque ZUP1 (96% identical), dog ZUP1 (88% identical), pig ZUP1 (87% identical), rabbit ZUP1 (85% identical), mouse Zup1 (82% identical), guinea pig ZUP1 (82% identical), rat Zup1 (81% identical), tropical clawed frog zup1 (56% identical), Drosophila melanogaster CG6654 (8% identical), Drosophila melanogaster dwg (7% identical), Caenorhabditis elegans pat-9 (6% identical). Paralogues in human: ZNF652 (12% identical), GTF3A (12% identical), ZBTB47 (11% identical), ZNF513 (10% identical), ZNF324 (9% identical), ZNF324B (9% identical).
Diseases named in the same sentence as ZUP1 in open-access papers:
ZUP1 is named in the same sentence as 83 diseases in open-access papers, as found by Europe PMC text mining. Sharing a sentence is not in itself a finding about the gene and the disease.
ZUP1 shares sentences with these, for which no sentence is quoted: cancer (110 papers); tumor (69); ovarian tumor (22); infection (16); breast carcinoma (10); viral infection (10); melanoma (9); lung carcinoma (8); hepatocellular carcinoma (7); neurodegenerative disease (6); glioma (4); lymphoma (4); prostate carcinoma (4); autoimmune disease (3); Machado-Joseph disease (3); acute myeloid leukemia (2); Autoimmunity (2); bladder cancer (2); cervical cancer (2); colon cancer (2); colorectal cancer (2); glioblastoma (2); hematological malignancies (2); kidney disease (2); lung adenocarcinoma (2); non-small cell lung carcinoma (2); osteosarcoma (2); ovarian carcinoma (2); acute lymphoblastic leukemia (1); Arthritis (1).
A further 53 diseases each share a sentence with ZUP1 in 1 paper.